MYCN (MYCN proto-oncogene, bHLH transcription factor)
Diseases named in the same sentence as MYCN in open-access papers (continued):
Sharing a sentence is not in itself a finding about the gene and the disease.
neuroblastoma (continued). "We therefore assessed PIK3CA for mutation in human neuroblastomas, as well as in neuroblastomas arising in transgenic mice with MYCN overexpressed in neural-crest tissues." (PMID 16822308, 2006). "High MKI was found in 55 out of 110 NTs (50%) and was associated with advanced stage (P=0.007), neuroblastoma (NB) histological category (P=0.024), MYCN amplification (P<0.001), and poor outcome (P=0.011)." (PMID 16755292, 2006). "The genetic alterations most frequently found in neuroblastoma are MYCN amplification and 1p36 allelic loss, both of them associated with a poor prognosis." (PMID 17064406, 2006). "The genetic alteration most frequently found in neuroblastoma is 1p36 allelic loss, which is associated with MYCN amplification and poor prognosis." (PMID 17064406, 2006). "Pik3ca, Ras family, and Braf activating mutations occur rarely in human neuroblastomas or in a murine model driven by neural-restricted MYCN overexpression." (PMID 16822308, 2006). "A major genetic feature of aggressive neuroblastoma tumours is amplification of the oncogene MYCN, and this is often associated with loss of chromosome region 1p." (PMID 16359544, 2005). "As loss of distal 11q is a recurrent chromosomal aberration in MYCN single copy advanced stage neuroblastomas, we propose the 11q25->11qter chromosomal segment as the most likely candidate region for the presence of a differentiation gene." (PMID 16000168, 2005). "MYCN amplification in neuroblastoma is associated with advanced stage, rapid tumour progression and poor prognosis." (PMID 11953858, 2002). "Rapid tumour progression in neuroblastoma is associated with MYCN amplification, deletion of the short arm of chromosome 1 and gain of 17q." (PMID 11044353, 2000). "As previously reported, 17q gain was significantly associated with metastatic stage 4 neuroblastoma and more frequently detected than both deletion of chromosome arm 1p and MYCN amplification in tumours of all stages." (PMID 10604740, 1999). "Advances in molecular biology and genomics have significantly improved understanding of neuroblastoma pathogenesis, revealing the critical role of genetic and epigenetic alterations-such as MYCN amplification, ALK mutations, and chromosomal aberrations-in disease behavior and prognosis." (PMID 41682783, 2026). "MYCN amplification, a hallmark of high-risk disease, drives an aggressive transcriptional program that maintains undifferentiated and proliferative states in neuroblastoma cells." (PMID 40867243, 2025). "Clinically, neuroblastoma patients are classified into low‐, intermediate‐, and high‐risk groups based on factors including age at diagnosis, disease stage, histopathological characteristics, MYCN amplification, and other genetic markers." (PMID 40984038, 2025). "In neuroblastoma MYCN amplification is associated with enhanced angiogenesis and poor survival." (PMID 40359728, 2025). "High-risk neuroblastomas with MYCN amplification show profound immune dysregulation, including altered immune cell infiltration and immune response gene expression, which could suggest a strategy of immune evasion unique to these tumors." (PMID 39860532, 2025). "MYCN oncogene amplification is the first independent prognostic factor indicating poor clinical outcomes of NB patients, observed in approximately 18% of cases, accounting for 40% of high-risk neuroblastomas." (PMID 41465323, 2025). "In addition, we observed that high KLHL37 expression was also associated with poor outcomes for patients with non-MYCN-amplified neuroblastoma." (PMID 40493396, 2025).
neuroblastoma (continued). "Ectopic expression of MYCN has been shown to enhance neurosphere formation in neural crest cells, a hallmark of stem cells, and to promote symmetrical cell division, which is associated with self-renewal in human neuroblastoma cells." (PMID 39802403, 2025). "Although activation of the TMM has been shown to be a key factor in the poor prognosis of neuroblastoma, MYCN amplification and ATRX mutations, the primary drivers of the TMM, are also associated with multiple modes of transcriptional activation that drive malignant transformation." (PMID 40115016, 2025). "However, it occurs in only approximately 18% of neuroblastoma patients, while nearly 80% present with single-copy MYCN—a subgroup that includes low- and intermediate-risk NB and remains comparatively less explored." (PMID 41465323, 2025). "MYCN amplification is associated with high vascularity and poor prognosis in neuroblastoma." (PMID 40359728, 2025). "Patients with neuroblastoma are commonly considered high-risk if they are older than 18 months old with metastatic disease or have local disease with concerning tumor characteristics such as MYCN amplification." (PMID 40136328, 2025). "MYCN amplification is particularly associated with HR neuroblastoma." (PMID 40708972, 2025). "Given the growing interest in targeting transcriptional dependencies in MYCN-amplified cancers, therapeutic inhibition of NIPBL will offer a promising strategy to disrupt MYCN-driven oncogenic networks and restore differentiation potential in high-risk neuroblastoma." (PMID 40867243, 2025). "Neuroblastoma translational research is being enhanced through the use of genetically-engineered mouse (GEM) models, such as the Th-MYCN mouse in which tumours spontaneously arise with native vasculature and recapitulate the disease biology of high-risk neuroblastoma in children." (PMID 40359728, 2025). "Using single-cell RNA-sequencing, we delved into the cellular and molecular foundation of early stage neuroblastoma development, discovering a unique neuroblastoma cell subtype and its transcriptomic signature associated with this regression-like phenomenon in Th-MYCN mice." (PMID 40580553, 2025). "Notably, high expression of KLHL37 in patients with MYCN-amplified neuroblastoma was associated with a worse prognosis compared with those with low KLHL37 expression." (PMID 40493396, 2025). "Among the cohort, 35.5% were high-risk patients, and 18.7% had MYCN-amplified neuroblastoma." (PMID 39860532, 2025). "High level of MYCN amplification is a driver of high-risk neuroblastoma." (PMID 40115016, 2025). "The reduced immune infiltration in MYCN-amplified tumors, linked to poor survival outcomes, underscores the role of an immunosuppressive microenvironment in neuroblastoma progression and highlights immune modulation as a potential therapeutic strategy for high-risk patients." (PMID 39860532, 2025). "Prior studies have found that MYCN amplification is associated with an increased risk of local failure for patients with newly diagnosed high-risk neuroblastoma, this finding may represent a false positive given the small size of the cohort." (PMID 40136328, 2025). "However, the survival rate of patients suffering from relapsed or refractory high-risk neuroblastoma was currently less than 15%131 and was even lower among patients with MYCN amplification." (PMID 39802403, 2025). "Moreover, high expression of the cluster is triggered by the primary neuroblastoma-associated oncogene, MYCN, and directly linked to enhanced cellular proliferation and impaired differentiation." (PMID 38994560, 2024). "However, Yu and colleagues reported the contradictory finding that low NORAD expression was associated with poor survival, MYCN amplification, and high-risk neuroblastoma." (PMID 38891878, 2024). "MYCN gene amplification is associated with increased invasiveness of neuroblastoma and plays a key role in promoting proliferation, invasion, and metastasis of neuroblastoma." (PMID 38959634, 2024).
neuroblastoma (continued). "ALDH18A1 is associated with the onset and progression of neuroblastoma and may influence tumor cell proliferation and self‐renewal through a positive feedback mechanism with the MYCN gene." (PMID 39350574, 2024). "Gene amplification in MYCN is the first genetic marker that indicates a highly invasive, advanced neuroblastoma, which has been observed in about 20% of primary and about 40% of high-risk neuroblastoma cases." (PMID 38553589, 2024). "MYCN amplification is one of the most important biological features of high-risk neuroblastoma." (PMID 38488852, 2024). "MYCN amplification is the most consistently observed independent genetic alteration linked to poor prognosis and treatment resistance in several pediatric malignancies, including neuroblastoma." (PMID 38338881, 2024). "Aberrant CCAT2 expression has been associated with aberrant MYCN expression in neuroblastoma." (PMID 38891878, 2024). "Finally, through a large scale reanalysis of available RNA sequencing data, Modi and colleagues identified a group of adrenergic neuroblastoma lncRNAs, which are MYCN-associated, as the adrenergic state is known to be dependent on MYCN." (PMID 38891878, 2024). "Notably, in high-risk MYCN-amplified neuroblastoma, H3K9 euchromatic histone lysine methyltransferase (EHMT) inhibitors in combination with EZH2 inhibitors exert immunomodulatory effects by inducing strong IFN-γ downstream responses." (PMID 39766049, 2024). "Intriguingly, MYCN-regulated translation has recently been reported as a therapeutic vulnerability in medullo-blastoma, and our studies support this possibility in high-risk neuroblastoma." (PMID 39313128, 2024). "Surprisingly, MYCN-amplified neuroblastoma cells are particularly susceptible to ferroptosis." (PMID 38908072, 2024). "To determine whether this impaired growth in MYCN-amplified neuroblastoma is linked to cell cycle perturbations, we used an 5-ethynyl-2′-deoxyuridine (EdU) and propidium iodide (PI) incorporation assay to assess progression through the cell cycle." (PMID 38820154, 2024). "In neuroblastoma, the PI3/Akt/mTOR pathway has been found to affect multiple pathways/proteins to enhance the neuroblastoma phenotype, such as stabilizing MYCN, which in turn facilitates processes associated with malignancy like proliferation, angiogenesis, and metabolic reprogramming." (PMID 39319058, 2024). "These genes have previously been linked with MYCN-associated glutamine addiction in neuroblastoma." (PMID 39313128, 2024). "High-risk neuroblastoma is characterized by metastatic spread to the bone, bone marrow, or liver in patients who are greater than 18 months of age or whose tumors have amplification of the proto-oncogene MYCN." (PMID 38014922, 2023). "Also for neuroblastoma, amplification of the MYCN gene, gain of 17q and loss of heterozygosity of chromosome 1 have been found to be recurring events, occurring extremely early in tumor development and remaining present during the course of the disease." (PMID 37152023, 2023). "Interestingly, disulfiram significantly decreased the protein level of MYCN, which is the main oncogenic driver of high-risk neuroblastoma." (PMID 37777587, 2023). "Specifically, overexpression of Aurora A mRNA in neuroblastoma tumor tissue was shown to be associated with high-risk disease, higher stage, unfavorable histology, MYCN amplification (p = 0.017), disease relapse (p = 0.019), and decreased progression-free survival." (PMID 37835416, 2023). "We found significantly reduced penetrance of MYCN-driven neuroblastoma in transgenic zebrafish with the T/T allele at the rs2168101 locus, concurrent with decreased lmo1 expression by these tumors, supporting our previous studies in neuroblastoma cell lines." (PMID 37183825, 2023).
neuroblastoma (continued). "About half of patients with neuroblastoma are classified as having high-risk disease, by a combination of factors including age at diagnosis, extent of disease, histological findings, and cytogenetic characteristics such as MYCN amplification and DNA ploidy." (PMID 37628301, 2023). "When CT and MRI combined with serum MYCN mRNA level detection, the diagnostic probability of neuroblastoma may be higher, and the sensitivity was significantly improved." (PMID 37592273, 2023). "Shortly after its discovery, MYCN was associated with high-risk neuroblastoma and poor prognosis." (PMID 38001143, 2023). "Our results provided new prognostic functions of ZNF436 in neuroblastoma and those prognostic functions may be associated with unique MYCN amplification and 1p deletion." (PMID 37904225, 2023). "The occurrence of MYCN amplification in approximately 20% of neuroblastomas, which correlates with high-risk disease and poor prognosis, further underscores the importance of MYC and HIF signaling pathways in these adrenal neoplasms derived from the neural crest." (PMID 37361539, 2023). "Hence, we used genome editing technology to introduce the T-containing allele into the zebrafish germline and then bred this allele into our MYCN driven neuroblastoma model." (PMID 37183825, 2023). "However, only 20% and 10% of neuroblastoma tumors harbor MYCN amplification or ALK mutation, respectively." (PMID 37152023, 2023). "Previous research revealed that rap inhibits neuroblastoma cell proliferation by reducing MYCN protein expression, which may be associated with the PI3K/AKT/mTOR pathway." (PMID 36978413, 2023). "The biology of neuroblastoma and its underlying developmental mechanisms have been progressively elucidated by advanced studies beyond the context of MYCN amplifications that have been mapped both across the endogenous locus and in structures of extrachromosomal DNA amplicons (ecDNA)." (PMID 37835497, 2023). "Consequently, these signatures were highly prevalent in high-risk MYCN-amplified neuroblastomas (p < 2.5 × 10−2), which contain focal amplifications." (PMID 37868040, 2023). "It is worth noting that a large number of clinical data have shown that patients with high-risk neuroblastoma are often accompanied by abnormal amplification and high-level expression of the MYCN gene, suggesting that the MYCN gene plays an important role in tumor malignancy and development." (PMID 36770809, 2023). "Moreover, it was observed that NCAPG exhibited significant upregulation in individuals with neuroblastoma who had MYCN amplification, high-risk, high-stage disease, and tumor advancement." (PMID 37834394, 2023). "Substantial evidence revealed that the frequency of allelic loss at 11q23 was inversely related to MYCN amplification in neuroblastomas, a common region of deletion that harbours a series of proteins that play a central role in the DSB repair pathways such as ATM, MRE11, and H2AFX." (PMID 37240360, 2023). "In view of MYC/N similarity and strongly associated expression of IGF2BP1 and MYCN in neuroblastoma, we hypothesized that MYCN promotes IGF2BP1 transcription as well." (PMID 37246217, 2023). "I believe that insights provided in this minireview could help develop new ideas and strategies to counter tumor metastasis in MYCN-driven high-risk neuroblastoma." (PMID 37274289, 2023). "In addition to MYCN amplification, aggressive neuroblastoma is also associated with activating mutations of the ALK oncogene and the overexpression of the epigenetic regulator involved in development, LIN28B." (PMID 37444423, 2023). "However, ATRX mutations and MYCN amplification are incompatible in neuroblastoma of all ages and stages." (PMID 37190157, 2023). "Importantly, it should be noted that one of the current chemotherapy regimens COJEC, has been associated with the induction of M2 macrophages in MYCN-amplified neuroblastoma." (PMID 38087370, 2023).
neuroblastoma (continued). "Finally, a recent report linked activation of the MYC paralogue MYCN in neuroblastoma to dependence on cysteine import and synthesis, needed to produce glutathione and avoid ferroptotic cell death." (PMID 37158102, 2023). "High MYCN/c-MYC target gene expression is a hallmark of malignant neuroblastoma progression." (PMID 37361539, 2023). "We then focused on a subset of high-risk neuroblastoma patients with MYCN amplification to determine whether the MYCN amplification status in patients uniquely drives the improved survival associated with T cell gene expression." (PMID 36068918, 2023). "Abnormal MYCN amplification and the consequent overexpression of the oncoprotein, N-Myc, which occurs in 20%–25% of patients with neuroblastoma and 50% of high-risk cases, is the most important promoting factor and the best-characterized genetic marker for poor prognosis of neuroblastoma." (PMID 37991019, 2023). "Consistent with its anti-apoptotic function, the increased levels of ΔNp73 expression are significantly associated with poor survival in patients with neuroblastomas, whereupon it predicts worse outcome independently of other risk factors such as patient age and MYCN amplification." (PMID 36831211, 2023). "We reveal a suppressive function of MYCN on circRNA biogenesis in high-risk neuroblastoma." (PMID 37402719, 2023). "This may be due to the fact that MYCN, as a risk factor with independent prognostic ability, has a greater influence on the image features of neuroblastoma." (PMID 37316589, 2023). "IBL-302 also diminished MYCN expression in neuroblastoma cells, but whether this is attributable to a loss of PIM activity is unknown." (PMID 37414143, 2023). "Additionally, loss or silencing of caspase 8 expression is associated with MYCN-amplified and aggressive neuroblastomas." (PMID 35568716, 2022). "Univariate analysis identified a high LDH value (P = .001) and high DIC score on admission (P = .006), fever preceding induction therapy (P = .012), and MYCN amplification (P = .003) as possible risk factors of ARE in patients with newly diagnosed neuroblastoma." (PMID 34255936, 2022). "Therefore, MYCN has been considered a strong predictor of poor prognosis and mortality and an attractive target for therapeutic intervention in high-risk neuroblastoma." (PMID 36187481, 2022). "Future studies should investigate the EV-based method as an adjunct to the standard procedures, assessing its diagnostic performance in the large prospective cohort and evaluating its clinical impact on the early treatment initiation in patients with MYCN-amplified high-risk neuroblastoma." (PMID 35681607, 2022). "The telomerase dependent pathway is activated through transcriptional upregulation of the gene telomerase reverse transcriptase (TERT) which is most frequently caused by amplification of the oncogene MYCN or by rearrangements of the TERT locus in neuroblastoma." (PMID 36153564, 2022). "Interestingly, gene set enrichment analysis (GSEA) revealed OXPHOS (oxidative phosphorylation) as the most prominently upregulated hallmark pathway in MYCN-amplified neuroblastoma cells, which is associated with an upregulation of the MYC-targeted pathway." (PMID 35805002, 2022). "Taschner-Mandl and collaborators found that metronomic topotecan in vitro (5 nM for 3 weeks) selectively promoted DNA damage and a tumor-inhibiting favorable senescence-associated secretory phenotype (SASP) in aggressive MYCN-amplified neuroblastoma cells (i.e., STA-NB-10 and CLB-Ma)." (PMID 36362482, 2022). "However, in the course of the disease, a metastatic relapse with progression to stage 4 was diagnosed with a concomitant switch to MYCN amplification of his neuroblastoma, changing the patient’s status from low-risk to high-risk at the time of relapse." (PMID 36497290, 2022).